IRF4 (interferon regulatory factor 4)
Diseases named in the same sentence as IRF4 in open-access papers (continued):
Sharing a sentence is not in itself a finding about the gene and the disease.
Achalasia (1 paper, 2016). A disorder of esophageal motility characterized by the inability of the lower esophageal sphincter to relax during swallowing and by inadequate or lacking peristalsis in the lower half of the body of the esophagus. "Interestingly, in our results, IRF4 and BLIMP1 are important upstream regulators of genes down-regulated, such as XBP1, IGHM, CD79A, RORC, and IKZF2, stressing the implications of the immune-inflammation network in achalasia." (PMID 27511445, 2016).
albinism (1 paper, 2013). A congenital disorder characterized by partial or complete absence of melanin pigment in the eyes, hair, or skin. "In addition to ASIP, IRF4, KITLG, MC1R, SLC24A4, and TYRP1, we chose 41 additional candidate genes with a potential role in human skin color based on their phenotypes in model organisms, or in humans affected with albinism." (PMID 23555287, 2013).
aspergillosis (1 paper, 2022). Aspergillosis is an infection, growth, or allergic response caused by the Aspergillus fungus. "Therefore, polymorphisms of many immune-related genes are associated with susceptibility to aspergillosis, such as tumor necrosis factor receptor 1 (TNFR1), TLR1/4/5/6, Dectin-1, DC-SIGN, IL-8, IL-10, IL-12, IL-4R, IFN-γ, IRF4 and so on." (PMID 35407478, 2022).
Blau syndrome (1 paper, 2022). Blau syndrome (BS) is a rare systemic inflammatory disease characterized by early onset granulomatous arthritis, uveitis and skin rash. "Thus, inflammation characterizing Blau syndrome are caused, at least in part, by faulty canonical signaling and reduce IRF4-mediated cross-regulation." (PMID 36189261, 2022).
brain injury (1 paper, 2021). Acute and chronic (see also brain INJURIES, CHRONIC) injuries to the brain, including the cerebral hemispheres, CEREBELLUM, and brain STEM. "Similarly, previous studies have shown the high expression of IRF4 in the mice with ischaemic brain injury, while another study demonstrated the significantly up‐regulated expression of IRF4 in rats with MCAO." (PMID 33314611, 2021).
Breast invasive carcinoma (1 paper, 2021). "The IRF4 expression levels were lower in Bladder urothelial carcinoma (BLCA), Breast invasive carcinoma (BRCA), Colon adenocarcinoma (COAD), Kidney chromophobe (KICH), Liver hepatocellular carcinoma (LIHC) and Rectum adenocarcinoma (READ)." (PMID 34195096, 2021).
Cervical lymphadenopathy (1 paper, 2023). Enlarged lymph nodes in the neck. "The LBCL, IRF4+ cases in the current study present most frequently with cervical lymphadenopathy or tonsillar masses." (PMID 37081786, 2023).
cognitive decline (1 paper, 2021). "In addition, our finding regarding MUM1 (also known as interferon regulated factor 4, IRF4) is noteworthy for its association with cognitive decline." (PMID 34857756, 2021).
Cognitive impairment (1 paper, 2021). Abnormal cognition is characterized by deficits in thinking, reasoning, or remembering. "Rats with intracerebroventricular injection of β-amyloid resulted in cognitive impairment and imbalance between IRF4 and IRF5, which was rescued by M2 macrophage transplantation." (PMID 34857756, 2021).
dengue (1 paper, 2023). "In children and adults, gene ontology biological process (GOBP) terms calculated (p adj <= 0.05) using markers reflected increased interferon signaling in primary dengue, driven by increased expression of genes including IFITM2 and IRF4 in adults and GPX1 and TCEB2 in children." (PMID 37638019, 2023).
eosinophilia (1 paper, 2019). "Abolished GATA3, IRF4, and BATF expression in Stim1/2-deficient Tregs may thus explain the type 2 autoimmunity in Stim1/2Foxp3 mice, which is characterized by elevated Th2 cytokines, increased IgE levels and eosinophilia." (PMID 30862784, 2019).
esophageal cancer (1 paper, 2024). A primary or metastatic malignant neoplasm involving the esophagus. "In addition, overexpression of IRF2 promotes esophageal cancer cell proliferation and mutations of SNPs in genes such as IRF3, IRF5, and IRF7 may facilitate the progress of esophageal cancers, while IRF4 may be regarded as a protective factor in ESCC." (PMID 39384770, 2024).
glomerulonephritis (1 paper, 2024). A renal disorder characterized by damage in the glomeruli. "Despite the suppressive function of IRF4 in plasma levels of TNF and IL-12p40, IRF4 deficiency completely protected B6/lpr mice from glomerulonephritis." (PMID 38256157, 2024).
glucose metabolism disorder (1 paper, 2020). "IPA analysis indicates that loss of IRF4 in skeletal muscle may contribute to glucose metabolism disorder." (PMID 33042761, 2020).
gout (1 paper, 2025). A condition characterized by painful swelling of the joints, which is caused by deposition of urate crystals. "For example, for the motifs IRF1 and IRF4, these are involved in the regulation of immune response and may influence inflammatory pathways, which are known to be associated with urate metabolism and gout." (PMID 40745483, 2025).
Granuloma (1 paper, 2025). A compact, organized collection of mature mononuclear phagocytes, which may be but is not necessarily accompanied by accessory features such as necrosis. "Immune and parenchymal cells in granuloma-rich right lungs demonstrated robust upregulation of genes related to immune activation, chemokine/cytokine signaling, and antimicrobial defense (CXCL, CCR, IL2, IRF4, GZMK)." (PMID 41586350, 2025).
hemarthrosis (1 paper, 2025). Bleeding into the joints. "Among the three M2 markers unaltered by hemarthrosis (Arg1, Chil3, Irf4), Arg1 and Chil3 demonstrated a notable decrease and increase with rhFVIII, respectively, while relatively unaffected (similar to baseline) with mFcFVIII." (PMID 40388523, 2025). "Pertaining to M2 markers, six of eight M2 markers were affected (up-/down-regulated with hemarthrosis and/or affected by FVIII-treatments) on day 3 and 14 (Arg1, Chil3, Mmp9, Fcgr4, Pparg, Irf4)." (PMID 40388523, 2025).
Hepatic steatosis (1 paper, 2023). Steatosis is a term used to denote lipid accumulation within hepatocytes. "Skeletal muscle specific IRF4 knockout (F4MKO) mice exhibited ameliorated hepatic steatosis, inflammation, and fibrosis, without changes in body weight, when put on a nonalcoholic steatohepatitis (NASH) diet." (PMID 37770480, 2023).
intestinal infection (1 paper, 2023). "In both models of intestinal infection, we observed defective accumulation of Irf4 heterozygous and particularly Irf4 homozygous mutant CD4+ T cells in SI and colon." (PMID 37469513, 2023).
intestinal tumors (1 paper, 2022). "We confirmed an increased level of plasma cells in diffuse versus intestinal tumors using IRF4 (a plasma cell marker) IHC on a subset of tumors (n = 17, P = 0.036)." (PMID 34642171, 2022).
keloid (1 paper, 2025). An irregularly shaped, elevated mark on the skin caused by deposits of excessive amounts of collagen during wound healing. "Notably, pivotal regulators for each sub-fibroblast cluster were discovered: IRF4 for scar, CLOCK for keloid, RUNX3 for scleroderma, and HOXC4 for normal skin." (PMID 41350567, 2025). "Additionally, we identified the pivotal regulators of each specific sub-fibroblast cluster, including IRF4 for scar-related, CLOCK for keloid-related, RUNX3 for scleroderma-related, and HOXC4 for normal skin sub-fibroblast clusters." (PMID 41350567, 2025).
Large vessel vasculitis (1 paper, 2013). A type of vasculitis (inflammation of blood vessel walls) affecting large arteries such as the aorta and branches of the aorta. "In their study, mice deficient in interferon regulatory factor-4, a protein that inhibits IL-17A production, rapidly developed large-vessel vasculitis and showed increased IL-21 synthesis in addition to increased IL-17A production." (PMID 23799890, 2013).
latent infection (1 paper, 2014). "Moreover, we profiled the IRF4 transcriptome in the context of EBV latent infection, and confirmed several genes including IFI27, IFI44, GBP1, and ARHGAP18, as well as CFLAR as novel targets for IRF4." (PMID 25207815, 2014).
lupus nephritis (1 paper, 2018). Glomerulonephritis in the context of systemic lupus erythematosus. "For example in a murine model of SLE, IRF4 knockout mice did not develop lupus nephritis." (PMID 30340504, 2018).
lupus-like syndrome (1 paper, 2015). "Here we have employed mice that lack the expression of DEF6 and SWAP-70, two molecules known to restrain IRF4 function in T and B cells, to explore the contribution of DC-IRF4 to the lupus-like syndrome that develops in these mice." (PMID 26544714, 2015).
Lymphadenopathy (1 paper, 2021). Enlargement (swelling) of a lymph node. "Mice with global deletion of irf4 develop progressive, generalized lymphadenopathy by 4 to 5 weeks of age, establishing the requirement of IRF4 for the function and homeostasis of mature B and T lymphocytes." (PMID 33803441, 2021).
membranous nephropathy (1 paper, 2020). "Furthermore, in cultured human podocytes, TWEAK increased the expression of PLA2R as well as the expression of other genes recently identified by GWAS as linked to membranous nephropathy: NFKB1 and IRF4." (PMID 32664235, 2020).
metastatic melanoma (1 paper, 2025). A melanoma that has spread from its primary site to another anatomic site. "Multiplex immunofluorescence staining of sentinel lymph node tissues from metastatic melanoma patients confirmed protein-level co-expression of IRF4 with IRF8 in CD11C + CCR7+ mregDCs." (PMID 40890106, 2025).
Miscarriage (1 paper, 2015). A pregnancy that ends at a stage in which the fetus is incapable of surviving on its own, defined as the spontaneous loss of a fetus before the 22th week of pregnancy. "Interestingly, a notably higher level of Tim-3 was produced by DSCs from normal pregnancy than from miscarriage, which was associated with higher IRF4 expression and Th2 cytokine production by DSCs." (PMID 25757669, 2015).
myelofibrosis (1 paper, 2021). A partial or complete replacement of the bone marrow stroma by fibrous tissue. "In this context, we evaluated the IRF4 expression in 119 newly diagnosed consecutive Philadelphia negative MPNs (Ph- MPNs), showing a low expression among the MPNs phenotypes with a more significant decrease in primary myelofibrosis patients." (PMID 34952638, 2021).
myelolipomas (1 paper, 2024). "Expression of IRF4, a lymphocyte-specific interferon regulatory transcription factor involved in tumorigenesis, was also upregulated in CAH adrenals and myelolipoma compared to normal tissues (p < 0.001)." (PMID 38473790, 2024).
myocardial infarction (1 paper, 2018). Gross necrosis of the myocardium, as a result of interruption of the blood supply to the area, as in coronary thrombosis. "As cardiac cDC2s were largely unaffected by loss of IRF4 in the EAM model and myocardial infarction, it is also possible that cDC2s or MCs acted locally in the heart to activate effector autoreactive CD4+ T cells." (PMID 30524444, 2018).
nasal polyp (1 paper, 2022). "Western blot results showed that the expression of IRF4 in nasal polyps was significantly higher than that in the control group (p value < 0.0001)." (PMID 35697826, 2022). "In GSE179265, the expression of MIAT (p value = 0.0003) and IRF4 (p value = 0.0042) significantly up-regulated in the nasal polyp group than control group." (PMID 35697826, 2022). "In this study, we found that IRF4 was markedly expressed in epithelial cells as well as macrophages in the nasal polyp tissues." (PMID 35697826, 2022). "We found that the production of IRF4 was upregulated in nasal polyps." (PMID 35697826, 2022). "Therefore, we consider the MIAT/miR-125a/IRF4 subnetwork to be a potential key regulatory axis in the ceRNA network, which may play a critical role in the pathogenesis of nasal polyps." (PMID 35697826, 2022). "Immunohistochemistry showed that IRF4 is expressed in mucosal epithelium and macrophages of lamina propria in nasal polyp tissues, and the numbers of IRF4 positive cells in epithelium and lamina propria were marked enhanced in nasal polyp tissues in comparison with those in control tissues." (PMID 35697826, 2022).
osteoporosis (1 paper, 2022). A condition of reduced bone mass, with decreased cortical thickness and a decrease in the number and size of the trabeculae of cancellous bone (but normal chemical composition), resulting in increased fracture incidence. "In summary, IRF4/miR-636/DOCK9 axis was a promising target for the treatment of osteoporosis." (PMID 35397366, 2022). "Furthermore, the downstream target genes of miR-636 were identified, and the effect of IRF4/miR-636/DOCK9 on osteogenic differentiation was investigated for the treatment of osteoporosis." (PMID 35397366, 2022). "In summary, this paper proposed that IRF4/miR-636/DOCK9 may be considered as targets for the treatment of osteoporosis (OP)." (PMID 35397366, 2022).
Pan (1 paper, 2023). "Pan cancer analysis revealed the difference of IRF4 in different Tumor tissues and Normal tissues." (PMID 36797470, 2023).
pancreatic ductal adenocarcinoma (1 paper, 2020). An infiltrating adenocarcinoma that arises from the epithelial cells of the pancreas. "T110299 tumors from both control and Irf4−/− mice showed a moderately differentiated tubular to tubulo-papillary adenocarcinoma pattern with similar amounts of desmoplastic stroma and moderate chronic inflammatory infiltrates, resembling human pancreatic ductal adenocarcinoma." (PMID 32448983, 2020).
pc (1 paper, 2021). "Unlike CHL, PAX5 is rarely expressed in pc-ALCL, but the transcriptional factor MUM1/IRF4 is positive in most cases of pc-ALCL." (PMID 34572893, 2021).
plasma cell leukemia (1 paper, 2024). An aggressive plasma cell neoplasm characterized by the presence of neoplastic plasma cells in the peripheral blood. "Therefore, IRF4/MUM1 expression should be included in additional tests to differentiate plasma cell leukemia." (PMID 39462364, 2024).
Pneumocystis infection (1 paper, 2023). "To further confirm this notion, we assessed the expression of Mmp12, Itgax and Irf4 in DEX-treated or untreated mice at 2 weeks post Pneumocystis infection." (PMID 37359523, 2023).
primary immunodeficiency (1 paper, 2025). "KEGG pathway analysis revealed significant enrichment of IRF4 in pathways such as hematopoietic cell lineage and primary immunodeficiency." (PMID 40073065, 2025).
respiratory allergy (1 paper, 2020). "The current study highlights STAT3 and IRF4 as possible effectors of PM exposure and inform future functional analyses to reveal the biological and pathological background of PM caused respiratory allergy." (PMID 32448264, 2020).
retinal degeneration (1 paper, 2022). Degeneration of the retina. "For instance, alpha antitrypsin treatment ameliorated retinal degeneration by polarizing microglia toward the M2 phenotype, partly through the regulation of IRF4/IRF8 in rd1 mice." (PMID 36670960, 2022).
retinoblastoma (1 paper, 2025). A malignant tumor that originates in the nuclear layer of the retina. "Moreover, in the high-ICI subgroup, CD83, HLA-DOA, IRF4, DOK3, and CXCR1 genes were also hypermethylated and thus associated with the presence of retinoblastoma." (PMID 41150792, 2025).
skin aging (1 paper, 2023). The gradual irreversible changes in structure of skin that occur as a result of the passage of time.. "Two genes IRF4 and CRELD2 have been implicated in skin aging measurement." (PMID 37924108, 2023).
steatosis (1 paper, 2023). Increased lipid within the cytoplasm of cells. "IRF4-specific deletion in skeletal muscle alleviated steatosis, inflammation, and fibrosis in the liver." (PMID 37770480, 2023). "In conclusion, FSTL1 overexpression could counteract the effects of skeletal muscle IRF4 ablation in steatosis, fibrosis, and inflammation in NASH mice." (PMID 37770480, 2023).
subarachnoid hemorrhage (1 paper, 2025). A serious neurological disorder characterized by intracranial hemorrhage into the subarachnoid space. "According to recent research, in a rat model of subarachnoid hemorrhage, Maresin 1 activates LGR6 to reduce neuroinflammation via the CREB/JMJD3/IRF4 pathway." (PMID 40227207, 2025).
synovitis (1 paper, 2018). Inflammation of a synovial membrane. "Since synovitis in OA is often associated with greater symptoms such as pain and joint dysfunction and may promote more rapid cartilage degeneration we explored a role for IRF4 and CCL17 in early synovitis in CiOA." (PMID 29622035, 2018).
Thrombocytosis (1 paper, 2022). Increased numbers of platelets in the peripheral blood. "IRF4 expression is associated with the clinical phenotype and clinical hematological response of hydroxyurea in primary thrombocytosis, which may lead to the progression of AML." (PMID 36211454, 2022).
Ureteral obstruction (1 paper, 2022). Obstruction of the flow of urine through the ureter. "Bone marrow transplantation experiment showed that wild-type mice received IRF4-/- bone marrow cells presented less myeloid fibroblasts activation in injured kidneys and exhibited much less kidney fibrosis after unilateral ureteral obstruction." (PMID 36159833, 2022).
uveitis (1 paper, 2021). An inflammatory process affecting a part of or the entire uvea. "In this study, we generated mice with targeted deletion of irf4 in the CD4 T cell compartment and show that loss of IRF4 in CD4+ T cells conferred resistance to uveitis." (PMID 33803441, 2021). "Thus, the reduced level of Th17 with concomitant increase of Th1 cells in the eyes of CD4-IRF4KO mice during EAU underscores the requirement of IRF4 expression by T cells for pathogenesis of uveitis in mice." (PMID 33803441, 2021). "Thus, synergistic effects of IRF4 and IkZFs might induce metabolic reprogramming of differentiating lymphocytes and thereby dynamically regulate relative abundance of T and B lymphocyte subsets that mediate immunopathogenic mechanisms during uveitis." (PMID 33803441, 2021).
van der Woude syndrome (1 paper, 2015). Van der Woude syndrome (VWS) is a rare congenital genetic dysmorphic syndrome characterized by paramedian lower-lip fistulae, cleft lip with or without cleft palate, or isolated cleft palate. "IRF4 is a lymphocyte specific factor and the IRF6 gene is largely uncharacterised except for an association with van-der-Woude-syndrome." (PMID 25856589, 2015).